IL1B (interleukin 1 beta)
Diseases named in the same sentence as IL1B in open-access papers (continued):
Sharing a sentence is not in itself a finding about the gene and the disease.
lung adenocarcinoma (continued). "Here, we review the current understanding of the bridge between TAM metabolism, IL-1β signaling, and effector functions in lung adenocarcinoma and address the challenges to successfully incorporating these pathways into current anticancer regimens." (PMID 30832375, 2019). "The results were in agreement with earlier studies that postulated urethane induce over expression of key molecules such as NF-κB, Stat3, pStat3; IL-1β, those play a major role in chronic inflammation and lung adenocarcinoma." (PMID 28240047, 2017). "Stimulation of A549 human lung adenocarcinoma cells with IL-1β revealed an increase in COX-2 expression and endogenous synthesis of PGE2, accompanied by the downregulation of 15-PGDH." (PMID 25202373, 2014). "Furthermore, the target gene implicated in lung adenocarcinoma and the ERK signaling pathway was identified as IL-1B, showing a more pronounced survival curve." (PMID 39911279, 2025). "A study on the mycobiome in lung adenocarcinoma has shown that Aspergillus sydowii stimulates the production of the key molecule IL-1β through the b-glucan-mediated Dectin-1/CARD9 signaling pathway, thereby inducing MDSCs differentiation and promoting the formation of a tumor-suppressive TIME." (PMID 39408814, 2024). "Positive correlations were identified between IL-1β expression and the infiltration of immunosuppressive MDSCs, as well as the expression of their chemoattractants in patients with K-ras-mutant lung adenocarcinoma (KM-LUAD), suggesting the therapeutic potential of IL-1β blockades." (PMID 38520006, 2024). "To account for complexity of cell-to-cell contacts and formation of a hypoxic core formed under 3D growth conditions, we tested whether IL-1β–mediated induction of IDO1 in lung adenocarcinoma cells was conserved in a spheroid model of cell culture." (PMID 37985999, 2023). "We found that an inflammatory signature and cytolytic T cell score correlate with increasing ENPP2 expression in human lung adenocarcinoma patients, which is in line with findings in the literature that inflammatory cytokines like IL-1β, TNF-α, and IFN-γ can promote ATX expression." (PMID 37655662, 2023). "Patients with lung adenocarcinoma show higher levels of serum IL-1β compared to healthy individual." (PMID 37985999, 2023). "This indicates that IL-1β could be coactivating other pathways or transcription factors to induce PD-L1 and PD-L2 expression in lung adenocarcinoma cells." (PMID 37985999, 2023). "When stratified by histopathology, it should be noted that the studied IL1B htSNPs were only associated with risks among patients with lung squamous cell carcinoma and not among patients with lung adenocarcinoma." (PMID 37147350, 2023). "In A549 lung adenocarcinoma cells, nonthermal plasma was shown to enhance the anti-tumor activity of macrophages by releasing proinflammatory cytokines including IL1β to cause tumoricidal activity." (PMID 32973969, 2020). "In addition, TNF-α and interleukin-1β (IL-1β) induced pS-EphA2 in human lung adenocarcinoma A549 cells." (PMID 26158630, 2015). "Stem cell factor (SCF) (OR = 1.150, 95% CI: 1.021–1.296, P = 0.021) and interleukin-1beta (IL-1β) (OR = 1.152, 95% CI: 1.003–1.325, P = 0.046) were positively associated with lung adenocarcinoma risk, though no inflammatory factors showed causal links to squamous cell lung cancer risk." (PMID 38957317, 2024). "Therefore, blocking IL-1β may be a promising therapeutic strategy for K-ras–mutant lung adenocarcinoma." (PMID 38066523, 2023). "IL-1β and TNFα were shown to downregulate 15-PGDH expression in A549 human lung adenocarcinoma cells with concomitant induced COX-2 expression." (PMID 33596205, 2021). "Results demonstrated that the IL-1β/NF-κB signaling pathway was one of the critical signaling pathways of FZQX prescription regulating MDSCs to prevent the recurrence and metastasis of lung adenocarcinoma." (PMID 34055197, 2021).
lung adenocarcinoma (continued). "Subsequently, it is verified that 9 core targets for ginseng treatment of lung adenocarcinoma, namely, JUN, IL-1β, IL-2, ICAM1, HMOX1, MMP9, MMP2, PTGS2, and TNF, are closely related to the proliferation, migration, and apoptosis of lung adenocarcinoma cells." (PMID 32802118, 2020). "IL1A is linked to a poor prognosis in lung adenocarcinoma (LUAD), unlike IL1B, indicating a potential role of IL1A in promoting LUAD tumor progression." (PMID 40612864, 2025). "Our study uncovered a significant positive correlation between IL-1B expression and the ERK signaling pathway, suggesting that inhibiting the IR could potentially reduce the proliferation of lung adenocarcinoma cells." (PMID 39911279, 2025). "For instance, studies have shown that blocking IL-1β in K-ras mutant lung adenocarcinoma (KM-LUAD) mice, which express high levels of IL-1β in the lungs, significantly reduces tumor load when IL-1β monoclonal antibodies are administered at 6 and 14 weeks of age." (PMID 38571500, 2024). "Although A549 and H1792 cell lines had high expression of TDO2, none of the lung adenocarcinoma cells showed a significant induction with IL-1β stimulation." (PMID 37985999, 2023). "Our studies demonstrate that lung adenocarcinoma cells, but not normal immortalized lung epithelial cells, respond to IL-1β signaling by inducing the expression of parallel immune checkpoint proteins that have the potential to promote immune evasion." (PMID 37985999, 2023). "Our data indicate that regardless of the driver mutations, lung adenocarcinoma cells induce immunosuppressive IDO1 mRNA and protein, but not TDO2, in response to IL-1β stimulation." (PMID 37985999, 2023). "Thus, a reduced expression of IL-1β, TNF-α, and IL-6 and an enhanced expression of IL-10 were observed in lung adenocarcinoma in mice treated with zotarolimus combined with 5-FU." (PMID 33925400, 2021). "Meanwhile, according to the results of qRT-PCR, it is speculated that ginseng can treat lung adenocarcinoma by up-regulated JUN, IL-1β, IL-2, ICAM1, HMOX1, MMP9, and MMP2 targets and down-regulated PTGS2 and TNF genes." (PMID 32802118, 2020). "Human lung adenocarcinoma (A549) cells were stimulated with IL-1β for 18 hours in the presence or absence of VA Qu Spez." (PMID 25664986, 2015). "Human lung adenocarcinoma-derived A549 cells were stimulated with IL-1β for 18 hours in the presence or absence of VA Qu Spez, a therapeutic preparation of Viscum album that grows on oak trees." (PMID 22028854, 2011). "However, in IL-1β-stimulated lung adenocarcinoma cells, these transcription factors did not affect the expression of PD-L1 or PD-L2." (PMID 37985999, 2023). "Considering our discoveries that IL-1β prompts the upregulation of CD274 and PDCD1LG2 mRNA, as well as PD-L1 protein in lung adenocarcinoma cell lines, it is conceivable that heightened tumor or circulating IL-1β might additionally enhance the PD-1/PD-L1 axis’s suppression of cytotoxic T-cells." (PMID 37985999, 2023). "To determine whether IL-1β regulates IDO1, TDO2, PD-L1, and PD-L2, we measured mRNA and protein levels in lung adenocarcinoma cells lines (A549, H1792, H1838, H2347, H2228, HCC364 and HCC827) grown in 2D or 3D and in immortalized normal lung epithelial cells (HBEC3-KT and HSAEC1-KT)." (PMID 37985999, 2023). "In addition, the mRNA expression of IL-1 receptors, IL-1R1 and IL-1RAcp (Minna lab dataset, dbGaP Study Accession is phs001823.v1.p1), and response to IL-1β stimulation, which was measured as fold change in CXCL8 induction, were detected in immortalized normal cells and lung adenocarcinoma cells." (PMID 37985999, 2023). "Thus, the expression of IL-1β and TNF-α in mice treated with zotarolimus combined with 5-FU could be largely suppressed in lung adenocarcinoma." (PMID 33925400, 2021).
lung adenocarcinoma (continued). "Previous clinical study has revealed that the FZQX prescription could effectively reduce the levels of inflammatory factors (IL-6, TNF-α, IL-1β) and negative immune cells (Treg, MDSCs) in postoperative patients with early-stage lung adenocarcinoma and improve the quality of life." (PMID 34055197, 2021). "Because of no clear conclusion confirming the specific role in lung adenocarcinoma, TLR4 attracts our attention, which enables to stimulate NLRP3 inflammasomes via enhancing the activation of nuclear factor-κB (NF-κB), releasing more pro-inflammatory cytokines like IL-1β and IL-18." (PMID 37553698, 2023).
infarction (47 papers, 2008 to 2025). A localised pathological necrosis of tissue resulting from obstruction of the blood supply usually by a thrombus, an embolus, or vascular torsion. "In our study, we emphasize the pivotal role of GSDMD in the acute setting post infarction since the association of GSDMD with microvascular injury remained independent even after adjustment for IL-1β." (PMID 37424923, 2023). "Targeting IL-1β also reduces the risk of new MI events in patients with previous history of infarction." (PMID 31417911, 2019). "In addition, levels of pro-inflammatory factors, including TNF-α and IL-1β, reflected the presence of infarction associated-aseptic inflammation." (PMID 36514154, 2022). "Surprisingly, both SN1 and SN2 treatments exerted comparable anti-inflammatory effects at day 1 post-MI, attenuating early post-infarction inflammation as reflected by the reduced expression of IL-1β and IL-6." (PMID 41301919, 2025). "HSYA effectively suppressed NLRP3 inflammasome activation in rats with MIRI, resulting in decreased IL-1β release and infarction size." (PMID 40271057, 2025). "Although canakinumab's mechanism is broad IL-1β inhibition, its success underscores the pathological role of IL-1β (largely produced by inflammasome-pyroptosis activity) in post-infarction inflammation." (PMID 40832143, 2025). "Firstly, macrophage polarization dynamics (especially NLRP3 inflammasome-driven M1 activation and therapeutic M2 polarization) have emerged as key regulators of post-infarction remodeling, with clinical trials demonstrating the efficacy of IL-1β inhibition." (PMID 40587711, 2025). "NLRP3 enhances the infarction process and promotes more myocardial cell death after reperfusion by increasing inflammation and Interleukin-1 Beta (IL-1β) secretion." (PMID 41331264, 2025). "Results showed that AM-SB significantly reduced infarction volume, inflammation (IL-1β, TNF-α), and pyroptosis-related markers (NLRP3, GSDMD, ASC, Caspase-1), while decreasing gliosis and improving cerebral metabolites." (PMID 39859214, 2025). "In a focal cerebral ischemia model, sevoflurane preconditioning reduced cerebral infarct size, improved neural function, and reduced apoptosis through anti-inflammation (e.g., by reducing tumour necrosis factor-alpha and interleukin 1-β (IL1-β) levels)." (PMID 38317957, 2024). "In the animal model of AMI, the injured myocardial cells released interleukin-1 alpha (IL-1α), while interleukin-1 beta (IL-1β) increased after infarction." (PMID 34568491, 2021). "In conclusion, we show in this clinically relevant model of myocardial IRI that complement inhibition of C5 reduces infarction size, possibly through reduction of IL-1β and E-selectin, and improves ventricular function." (PMID 28258298, 2017). "Although IL-1α and IL-1β remain the best-studied members of the family, emerging evidence implicates IL-18 and IL-33 in regulation of the post-infarction inflammatory reaction." (PMID 26273700, 2015). "IL-1β has been demonstrated to be significantly related to infarction and left ventricular function after MI." (PMID 25202335, 2014). "Moreover, injection of AAV-miR-30e-3p in CME- induced MI in a rat model limited infarct size, improved cardiac function, and reduced the serum level of cTnI, IL-18, and IL-1β." (PMID 38132140, 2023). "And inhibited brain IL-1β synthesis could reduce infarction and improve left ventricular function, this suggests that inhibiting IL-1β expression in brain could improve heart function." (PMID 25202335, 2014). "The neurobehavioral scores, infarction volumes, and the levels of IL-1β and IL-13 were detected." (PMID 23970940, 2013). "Moreover, the expressions of IL-1β and Arg-1 decreased more obviously in cEVs-treated hearts than that receiving nEVs treatment, indicating that cEVs treatment showed better efficiency in modulating the cardiac inflammatory response post infarction." (PMID 37978390, 2023).
infarction (continued). "The expression levels of inflammatory cytokines TNF-α, IL-1β, and CCN1 in the peri-infarction cortex showed an increase post-I/R, a decrease post-TGN-020 treatment, and a subsequent increase following ERK1/2 pathway activation." (PMID 37695472, 2024). "In particular, IL-1β, IL-1Ra, IL-6, and MCP-1 showed 3-fold higher values in patients with extensive infarction; for patients who died, IL-1β was 3-fold greater and MCP-1 showed just less than a 3-fold difference." (PMID 33711020, 2021). "The inflammasomes activate caspase-1, which cleaves pro-IL1β into active IL1β, to play a central role in inflammation in TBI and infarction." (PMID 32967118, 2020). "We monitored the mRNA levels of IL-1β, TNF-α, IL-6 and MCP-1 in border zone of left ventricular infarct by RT-PCR." (PMID 31164920, 2019). "Infarction induced marked P2X7R activation following a significant increase in cleaved caspase‐1 and IL‐1β protein levels compared with a relatively small increase in procaspase‐1 3 days post‐MI." (PMID 28470940, 2017). "Serum concentrations of IL-1β and TNF-α are typically in the low pg/ml range, with increases in serum concentrations found in post-infarction and diabetic patient (values ranging between 10–25 pg/ml)." (PMID 19032770, 2008). "However, in the present study IL-1β in the renal cortex was the only cytokine other than TGF-β2, of the six measured at 90-days post-infarction, which was significantly altered." (PMID 31988300, 2020). "Administration of a single intraperitoneal injection of a neutralizing anti-IL-1β antibody immediately after coronary ligation in a model of non-reperfused infarction significantly increased the incidence of cardiac rupture, reducing collagen accumulation in the infarcted area." (PMID 26273700, 2015). "Moreover, the difference between the small and large infarction groups and the control group in terms of the WBC count, IL-1β, IL-8, and IFN-γ was not statistically significant." (PMID 33375339, 2020).
intervertebral disc degeneration (47 papers, 2013 to 2026). "The IL-1β is a pro-inflammatory cytokine closely associated with the pathogenesis of intervertebral disk degeneration, with increased IL-1β production levels correlating with higher disease severity." (PMID 39682777, 2024). "A study that investigated the association between intervertebral disc degeneration and polymorphisms in genes encoding IL-1 showed that the odds ratio for disc bulges was 2.4 and 3.0, in carriers of the IL-1β + 3954 T and IL-1α -889 T a, respectively." (PMID 33494410, 2021). "KLF5 has also been shown to be associated with the inflammatory response in intervertebral disc degeneration, as it is involved in IL-1β-activated NF-κB cascade by enhancing p65 phosphorylation and p65 acetylation." (PMID 34551684, 2021). "The inflammatory response is induced by the overexpression of inflammatory cytokines, mainly interleukin (IL)-1β, and is one of the main causes of intervertebral disc degeneration (IVDD)." (PMID 32133213, 2020). "Additionally, a causal relationship was confirmed between serum IL-1β level and intervertebral disc degeneration (OR 1.087; 95 % CI, 1.023–1.154; p = 0.007)." (PMID 39286222, 2024). "The major inflammatory cytokine IL‐1β is associated with intervertebral disc degeneration; however, the molecular mechanisms that drive IL‐1β production in the intervertebral disc, especially in nucleus pulposus (NP) cells, are unknown." (PMID 28224704, 2017). "The aim of this study is to investigate the effects of POSTN on IL-1β induced inflammation, apoptosis, NF-κB pathway and intervertebral disc degeneration (IVDD) in Nucleus pulposus (NP) cells (NPCs)." (PMID 38946726, 2024). "NPCs respond less strongly to IL-1β when the p38MAPK pathway is suppressed in animal experiments, suggesting that intervertebral disc degeneration is mediated by inflammation by silencing p38MAPK." (PMID 36945021, 2023). "In this study, we investigated the role of heme oxygenase-1 (HO-1) in intervertebral disc degeneration (IDD) by assessing the effects of HO-1 overexpression on IL-1β-induced apoptosis in nucleus pulposus cells (NPCs)." (PMID 32015215, 2020). "Intervertebral disk degeneration (IVDD) is a spinal disk condition caused by an inflammatory response induced by various proinflammatory cytokines, such as interleukin (IL)-1β and tumor necrosis factor (TNF)-α." (PMID 33015073, 2020). "IL‐1β has also been shown to be an important factor for intervertebral disc degeneration, whereby it stimulates a series of biochemical immune responses that cause dysfunction of the largest avascular tissue in the body, the intervertebral disc." (PMID 33098220, 2020). "A previous study verified that in degenerative and herniated intervertebral discs, the expression levels of IL-1α and IL-1β were correlated with the grade of intervertebral disc degeneration or the extent of intervertebral disc herniation." (PMID 30008976, 2018). "Next, we investigated the effects of T-5224 on mouse intervertebral disc degeneration induced by IL-1β in an ex vivo explant culture model." (PMID 29208967, 2017). "Inflammatory cytokines such as interleukin-1 beta (IL-1β) contribute to the progression of intervertebral disc degeneration." (PMID 26914760, 2014). "Furthermore, dual-targeting EVTPD effectively degraded both TNF-α and IL-1β and exhibited potent anti-inflammatory effects in rat and goat models of intervertebral disc degeneration." (PMID 41526766, 2026). "This competitive inhibition provides a potential mechanism for the anti-inflammatory effects of LN, as it may disrupt the IL-1β-mediated signalling pathways involved in intervertebral disc degeneration." (PMID 40305345, 2025). "Intervertebral disc degeneration and pain are associated with the nucleotide-binding domain, leucine-rich repeat, and pyrin domain-containing 3 (NLRP3) inflammasome activation and the processing of interleukin-1 beta (IL-1β)." (PMID 39456246, 2024).